MUC1 (mucin 1, cell surface associated)
Diseases named in the same sentence as MUC1 in open-access papers (continued):
Sharing a sentence is not in itself a finding about the gene and the disease.
cancer (continued). "Besides, the Muc1, which is a cell surface glycoprotein and overexpressed in various cancer, such as pancreatic, breast, lung, and stomach cancer, is utilized as a cancer-targeting biomarker." (PMID 32804261, 2020). "Muc1 is involved in the progression of various cancers, including PC." (PMID 32709695, 2020). "Importantly we found a correlation between the intensity of MUC1-ST staining of the cancer cells and CD163+ macrophages in the stroma around the nests of cancer cells." (PMID 33149188, 2020). "Importantly for TRT, cancer-specific MUC1 epitopes (MUC1-CE) are revealed on cancerous tissues andare largely indiscernible on normal tissues that have physiologic MUC1 expression." (PMID 33379259, 2020). "Other work revealed MUC1 to be part of a miR-322-dependent regulatory loop in human carcinomas." (PMID 33194611, 2020). "Indeed, a cancer-specific glyco-epitope on the Muc1 protein (Tn-Muc1) was recently shown to be an excellent target for CAR T cells against several types of cancers." (PMID 31171941, 2019). "Therefore, IGF-1R knock-down can prevent the up-regulation of MUC1 and epithelial-mesenchymal transition in cancer cells." (PMID 30041514, 2019). "The failure to detect MUC1, a most widely used cancer biomarker, might be due to technical difficulties to generate sufficient peptides by trypsin digestion." (PMID 30646616, 2019). "MUC1 (mucin 1) is a well-characterized member of membrane-bound mucins, modulates cell–to-cell and cell-extracellular matrix interactions and participates in cancer cell behaviors." (PMID 31666098, 2019). "In addition, human clinical studies utilizing MUC1 as a target should include blockade of Siglec-9 for improved clinical outcomes to patients with breast and other cancers." (PMID 31430935, 2019). "Therefore, the present findings should pave the way for the development of new anti-MUC1 mAbs with improved specificities to advance future cancer therapy." (PMID 31719620, 2019). "Using FACS analysis we could show that the mAb GGSK-1/30 specifically binds to these human MUC1 expressing murine cancer cells." (PMID 31588183, 2019). "Besides peptides, other monovalent vaccines were developed for HER2+ BC using other cancer-specific antigens such as MUC-1 vaccine in metastatic setting, WT1 vaccine for neodjuvant patients and gangliosides in adjuvant treatment, with some encouraging results." (PMID 31665051, 2019). "In fact, Muc1 is a target in several preclinical and clinical trials for cancer treatment." (PMID 30704051, 2019). "MUC1 is an attractive target for a therapeutic cancer vaccine that could induce cellular and humoral immune responses." (PMID 31468283, 2019). "Anti-MUC1 antibodies are also available against various cancers." (PMID 31514468, 2019). "We again see that patients with IPMN and cancer show higher average levels of anti-MUC1 IgG compared to healthy donors and importantly when IgG OD of each patient was paired with the same patient's percent of MDSC, there was a negative correlation (p = 0.132, r = −0.3941)." (PMID 31275327, 2019). "Indeed, four Muc1-based Phase III trials exploring cancer treatment have been completed, one of which used a Muc1 tandem repeat peptide as an immunogen (L-BLP25) in patients with stage III unresectable NSCLC after chemoradiation." (PMID 30704051, 2019). "Interestingly, over-expression of mucins, MUC-1 in particular, have been detected in many human malignancies and seem to promote cancer cell growth and survival." (PMID 31231358, 2019). "MUC1 overproduction was most commonly detected in poorly differentiated CCs, correlating with T category, gross type of intra- and extrahepatic CC, metastasis of lymph nodes, portal canal emboli and post-operational recurrence of the carcinomas." (PMID 30875782, 2019). "Thus, the abnormal glycosylation of MUC1 at cell surface is the key difference between cancer and healthy cells." (PMID 29857542, 2018).
cancer (continued). "MUC1 is the most abundant protein in cancer cells which bear the abnormally glycosylated O-glycans." (PMID 29857542, 2018). "Thus, the promoters of mucin genes, such as mucin 1 (MUC1), have been used to drive the expression of genes of interest in cancer cells." (PMID 29542355, 2018). "Studies on glyco-MUC1 epitopes in cancer versus healthy cells are currently ongoing." (PMID 29857542, 2018). "Furthermore, enhanced levels of the STn antigen can increase the invasiveness of cancer cells in a MUC1-dependent manner." (PMID 29912148, 2018). "However, MUC1 has emerged as a potential target for cancer therapy because it is overexpressed and functions in several types of cancers." (PMID 29987260, 2018). "MUC1 glycopeptide array may be used as the tool to evaluate the patients’ antibody response to cancer." (PMID 29857542, 2018). "A recent study on the stemness of cancer cells confirmed that during the passage of PDX mouse model, the stemness of cancer cells is gradually shaped by the murine microenvironment; this finding indicates that the expression of MUC1 can be altered in this progress." (PMID 29534550, 2018). "However, agents that target MUC1 in these approaches fail to reach the surface of the cancer cells because of the abundant expression of MUC1 in circulation and normal tissues." (PMID 29993037, 2018). "Interestingly, MUC1 levels are elevated by CpG demethylation in cancer cells, where promoter methylation plays an important role in determining MUC1 expression." (PMID 30518424, 2018). "Cytokine/growth factor-activated Src and STAT3 have been linked with promotion of EMT, migration, invasion, and angiogenesis in cancer cells, through induction of STAT3 downstream metastasis-associated proteins, including mucin 1 (Muc1), VEGF, and CXCR4, and by microtubule stabilization." (PMID 30149591, 2018). "MUC1 has been reported to be expressed by exosomes from both cancer cell lines and serum of cancer patients, although major technical challenges still exist for the practical application of using flow cytometry analysis to measure glycoprotein levels in exosomes." (PMID 29857542, 2018). "We also analyzed the expression of MUC1 in parental as well as in cancer cell derived stem cells." (PMID 30518424, 2018). "Early efforts have been focused on IgG1 antibodies which block the MUC1 in the surface of cancer cells, according to the rational that MUC1 is an oncoprotein which protects the cancer cells against apoptosis because the intracellular domain of MUC1 binds to BAX protein." (PMID 29857542, 2018). "Because of these properties, our vaccine targeting survivin and MUC1 might be broadly applicable for the treatment of various types of human cancer." (PMID 29415891, 2018). "Aptamers may have a use in targeting DNA origamis to cancer cells and a set of aptamers for cancer-specific Mucin 1 protein (MUC-1) have been integrated into a spherical DNA origami structure." (PMID 30477184, 2018). "The MUC1 glycoprotein was first identified as the antigen found in extracts of the human milk fat globule membranes, or in extracts of cancer cells, which induced a strong humoral response in mice, leading to the production of many monoclonal antibodies reactive with the TR domain." (PMID 29784646, 2018). "Further studies will be needed to investigate whether our findings in this study can be translated to other cancers in which MUC1 and ABCB1 are positive." (PMID 28796259, 2017).
cancer (continued). "Besides, several studies reported a biological role of MUC1 in cancer metastasis through disturbing cell adhesions." (PMID 27821817, 2017). "Therefore, MUC1 is a marker for poor prognosis in different types of cancers, as well as an ideal target for imaging because of its direct accessibility on membrane cells." (PMID 29261171, 2017). "Our data collectively support a model in which MUC1 induces acquired chemotherapy resistance by upregulating ABCB1 in an EGFR-dependent manner, providing a novel molecular basis of using the EGFR inhibitor in MUC1-positive cancers to prevent chemotherapy resistance." (PMID 28796259, 2017). "To investigate whether PTX-induced MUC1 was responsible for the observed resistance in cancer cells, we silenced the expression of MUC1 in HeLa229/TR cells." (PMID 28796259, 2017). "We highlight here that expression of MUC1 mRNA is higher than most mucins in a majority of cancers and may in part be fostered by increased demethylation of the promoter in multiple cancer tissues." (PMID 28978023, 2017). "In its role against cancer, MUC1 consists of two subunits: N- and C-terminal." (PMID 28512631, 2017). "MUC1 was induced in cancer cells upon treatment with chemotherapeutic drugs." (PMID 28796259, 2017). "Immune responses to a self- antigen are different from those to a foreign antigen; therefore our findings in the MUC1 mouse model cannot predict whether MVA- MUC1-IL-2 vaccine is a good candidate for therapeutic combination with radiation in cancer patients." (PMID 28116088, 2017). "MUC1 in particular is overexpressed in ~64% of tumors of all types diagnosed each year in the U.S., rendering MUC1 one of the most prominently dysregulated genes in cancer." (PMID 29266001, 2017). "The MUC1 ectodomain is sufficient to increase the metastatic potential of 4TO7 cancer cells." (PMID 29266001, 2017). "WFA-sialylated MUC1 showed significantly higher diagnostic sensitivity than CA19-9 for stage I and II carcinomas, and was also found to be superior to CEA for stage I, II, III, and IV carcinomas." (PMID 27358229, 2017). "These increased serum CA19-9 levels in advanced BTC/IhCC and in poorly differentiated carcinomas suggest that WFA-sialylated MUC1 could be applied as a biomarker with characteristics different from those of CA19-9." (PMID 27358229, 2017). "Furthermore, WFA-sialylated MUC1 levels were similar between carcinomas at early and advanced stages and between well-differentiated and undifferentiated carcinomas." (PMID 27358229, 2017). "In support of this, exogenous introduction of recombinant galectin-2, -4, or -8 at broadly pathological concentrations observed in cancer showed to induce changes of MUC1 cell surface localization and increase of cancer cell adhesion to endothelial monolayers in cell culture." (PMID 27066458, 2016). "In addition, MUC1 expression in cancer is usually characterized by a diffuse cytoplasmic staining pattern compared to apically restricted expression typically found in normal tissues." (PMID 27846218, 2016). "There were several studies about anti-MUC-1 vaccines for cancers." (PMID 27374181, 2016). "Other techniques that have been exercised by researchers for MUC1 vaccines include liposome based cancer vaccines, targeting CD8+ T cells to stimulate CTL activity, dendritic cell vaccines loaded with peptide, and dendritic cell vaccines loaded with mRNA or transfected with cDNA." (PMID 27472370, 2016). "In addition, DCs tend to adhere more to MUC1-STn+ cancer cells and this contact inhibits DC maturation, inducing them to produce IL-10 and reducing their ability to trigger the protective T helper 1 (Th1) response." (PMID 27754373, 2016). "Taken together, the microscopy and flow cytometry data indicated that the Apt-Td may serve as a carrier for targeted delivery of Dox to MUC1-positive cancer cells in vitro." (PMID 27203221, 2016). "MUC1 staining data were not available in 95 cases (7.2%) due to core loss or lack of cancer in the core samples." (PMID 27846218, 2016).
cancer (continued). "Due to the potential of MUC1 to serve as a broad-spectrum target for cancer treatment, it is necessary to explore new MUC1-targeted drug-delivery system designs, to facilitate the development of pharmaceutically implementable targeted chemotherapy against MUC1-expressing tumors." (PMID 27203221, 2016). "Importantly, hypoglycosylated MUC1 has also been found to be a target of immunosurveillance in cancer patients." (PMID 27545199, 2016). "Therefore, MUC1 STn and Tn forms are potential markers for early cancer diagnosis and prognosis and also targets for novel therapeutic strategies." (PMID 27754373, 2016). "Thus, human MUC1.Tg mice represent a very good model to investigate the role of the human MUC1 extracellular domain and its altered glycosylation in inflammation and cancer development." (PMID 27754373, 2016). "Moreover, in addition to Lin28B there are several putative cancer stem cell markers, such as MUC1, CD38, FLOT2, EGF and IKBKB that were also upregulated (signal log2 ratio>0.5) in mH2A1-depleted LD611 cells." (PMID 26028027, 2016). "However, despite the large number of early-phase trials, only a few MUC1 vaccine programs have reached stage III clinical trials, and therefore the long-term utility of MUC1 vaccination for cancer treatment or prevention remains to be determined." (PMID 27669306, 2016). "As similar to MUC1 and MUC16, MUC3A is also a membrane-associated mucin and maybe applied in serodiagnostic tests to diagnosis and monitor cancers." (PMID 27374181, 2016). "We found that 7 of the 13 antibodies were able to stain the majority of MUC1+ cancer cells lines." (PMID 27545199, 2016). "MUC1 is another mucin described in PM and is expressed on cancer cells." (PMID 27074785, 2016). "We used a large cohort to validate whether MUC1 protein levels measured by immunohistochemistry (IHC) predict aggressive cancer, recurrence and survival outcomes after radical prostatectomy independent of clinical and pathological parameters." (PMID 27846218, 2016). "In cancer tissues, expression of MUC1-ARF protein was highly dependent on the tissue in question." (PMID 27768738, 2016). "MUC1 expression in various types of cancer is an indicator of poorer prognosis." (PMID 27276704, 2016). "Finally, we assayed the CAR T cells for their ability to specifically lyse MUC1+ cancer cells by co-incubating CAR+ primary cells at various concentrations with ZR-75-1(MUC1low), T-47D (MUC1high) or HEK293T (MUC1−) target cells." (PMID 27545199, 2016). "MUC1 has been recognized as an important molecular target for cancer treatment." (PMID 27203221, 2016). "For MUC1-positive cancer cells, however, the binding between the aptamer and the cell may overcome the repulsive force and pull together the nanostructure and the cell." (PMID 27203221, 2016). "MUC1 itself is an oncoprotein and has been shown to be elevated in cancer cells; MUC1 secreted from TAMs could act to enhance tumorigenesis." (PMID 27276704, 2016). "Furthermore, acute inflammation was stimulated by trigger such as caerulein in vivo, which resulted in increased fluorescent signal of the cy5.5-EpCAM/muc1 ALB during cancer metastasis due to exogenous expression of EpCAM/muc1 in Panc02-implanted mouse model." (PMID 27886058, 2016). "Moreover, we recently reported the identification of CIN85 as a new partner of MUC1 and implicated the MUC1/CIN85 complex in invasion and metastasis of cancer cells." (PMID 25675408, 2015). "Meanwhile, contrary effects of MUC1 in cancer cells were reported in several independent studies." (PMID 26367866, 2015). "A recent report suggested that AGR2 may promote cancer cell invasion by increasing the expressions of MUC1 and lysosomal enzymes cathespin B and cathepsin D; thus, AGR2 overexpression plays an important role in invasion, grading, and prognosis of HNSCC." (PMID 25871396, 2015). "However, both distribution and biochemical features of MUC1 in cancer cells are different from those in normal cells." (PMID 26367866, 2015).
cancer (continued). "Successful targeting and photoablation of MUC1 positive cancer cells suggests these constructs may be useful anticancer therapeutics in the future." (PMID 26147830, 2015). "By analyzing the mRNA-seq reads from The Cancer Genome Atlas (TCGA), we uncovered a novel cancer-enriched chimeric RNA as the result of splicing between MUC1, a highly glycosylated transmembrane mucin, TRIM46, a tripartite motif containing protein, and KRTCAP2, a keratinocyte associated protein." (PMID 26492273, 2015). "In many cancers, MUC1 is aberrantly glycosylated and highly overexpressed." (PMID 26557640, 2015). "In addition, MUC1 prevents the interaction between immune cells and receptors on the cancer cell surface through steric hindrance." (PMID 26266422, 2015). "PANVAC is a cancer vaccine therapy that contains transgenes for the TAAs MUC-1 and carcinoembryonic antigen (CEA) as well as transgenes for three human T cell costimulatory molecules, collectively known as TRICOM (B7-1, intracellular adhesion molecule-1 and leukocyte function-associated antigen-3)." (PMID 25806106, 2015). "Despite encouraging results with two- and three-component MUC1 conjugate vaccines in mice models, immune tolerance to carbohydrate antigens remains a major obstacle in initiating an effective and long-lasting immune protection against malignancies." (PMID 25670999, 2015). "Importantly, after tumors have endured chemotherapy, which induces apoptosis, the macrophages produce a great change to the niche of the cancer stem cells, and stimulate cancer stem cells along with MUC1 expression." (PMID 26016502, 2015). "Taking into account its apparent involvement in such key biological processes as proliferation, survival, invasion, angiogenesis, apoptosis inhibition and chemoresistance, MUC1 is believed to play critical roles in carcinogenesis and, more likely, in cancer progression and metastasis." (PMID 26436698, 2015). "Imaging for MUC1 can demonstrate whether therapeutic targets are present in cancer cells and predict the treatment response of MUC1-targeted therapy." (PMID 25815753, 2015). "Since T antigens can be further extended to form more complex O-glycans, it should be noted that the effects of C1GALT1 on MUC1 and cancer cell behaviors could be resulted from core 1 and core 1 derived O-glycans." (PMID 25762620, 2015). "MUC1 is known to induce autoantibody formation in cancer patients." (PMID 25986064, 2015). "MUC1, in association with other molecules such as β-catenin, NF-kB p65 or EGFR, regulates transcription of several genes responsible for progression and invasiveness of cancer." (PMID 25675408, 2015). "MUC1 may be a useful target to identify and treat distant metastasis of all cancer types expressing the antigen using labeled or therapeutic-carrying antibodies." (PMID 25815753, 2015). "Several trials focusing on MUC-1 as a target for cancer immunotherapy in PCa are ongoing." (PMID 24834066, 2014). "Indeed, MUC1 has been considered as an oncoprotein, because there is accumulating evidence which suggests its cancer-promoting function." (PMID 24810688, 2014). "Is there any correlation between altered splicing and MUC1 overexpression in cancer?" (PMID 25261375, 2014). "Nonetheless,the role of MUC1 in cancer metastasizing remains far from clear." (PMID 25093113, 2014). "The obtained cells are used as an applicable model ofMUC1-expressing cancers and might be used to study the role of differentfunctional fragments of mucin MUC1 in metastasizing." (PMID 25093113, 2014). "CTLs for MUC1 only attack cancer cells with exposed tandem repeat domains." (PMID 25526950, 2014). "MUC1 has been known as an oncogene with an anti-apoptotic function in cancer cells; however, in normal gastric mucosa, it is anticipated that the mucin 1 protein has a role in protecting gastric epithelial cells from a variety of external insults which cause inflammation and carcinogenesis." (PMID 24810688, 2014).